CHD1L (chromodomain helicase DNA binding protein 1 like)
Diseases named in the same sentence as CHD1L in open-access papers (continued):
Sharing a sentence is not in itself a finding about the gene and the disease.
breast carcinoma (continued). "Also, we evaluated the expression of CHD1L in breast cancer cell lines." (PMID 25153161, 2014). "Pharmacological CHD1L inhibition with OTI-611 similarly enhances PARPi efficacy, promoting PARP1/2 trapping and PARthanatos in both BRCA-mutant and BRCA-wildtype breast cancer models." (PMID 40442742, 2025). "In breast cancer models, CHD1L transcriptionally upregulates MDM2, as shown by cDNA microarray analysis and confirmed via Western blot, where CHD1L overexpression increased MDM2 protein levels, and CHD1L knockdown reduced them." (PMID 40442742, 2025). "We also demonstrate that, as in breast cancer, OTI-611 traps CHD1L, PARP1, and PARP2 onto chromatin." (PMID 39684869, 2024). "CHD1L physically interacts with HIF-2α and enhances its downstream target gene expression by increasing the recruitment of BRD4 and RNA Pol II-S2P in breast cancer cells." (PMID 37691108, 2023). "The results demonstrated that CHD1L protein expression was significantly upregulated in LUAD, LIHC, glioblastoma multiforme, colon, and breast cancer tumor tissues in a comparison with a normal one (p < 0.001)." (PMID 37033447, 2023). "The expression of CHD1L protein and mRNA differed in MCF10A (human normal mammary epithelial cell line) and the two breast cancer cell lines (MCF-7, T-47D, SK-BR-3, and MDA-MB-231)." (PMID 26599012, 2015). "Thus, we hypothesize that CHD1L plays a crucial role in breast cancer cell invasion." (PMID 26599012, 2015). "In summary, the current study highlights for the first time that the presence of CHD1L over-expression in breast cancer patients, as measured by immunohistochemical analyses, is more likely to be associated with aggressive tumor biology rather than large tumor burden in breast cancer." (PMID 25153161, 2014). "One potential target is Chromodomain helicase DNA-binding protein 1-like (CHD1L, also known as ALC1), which is an oncogene that promotes tumor progression, metastasis, and multidrug resistance (MDR) in many cancers, including breast cancer." (PMID 39201277, 2024). "The ability of CHD1L protein to facilitate carcinogenesis is mainly due to its anti-apoptosis and epithelial-mesenchymal-transition(EMT)-inducing effects, which also plays an important role in the development of breast cancer." (PMID 25153161, 2014). "CHD1L is an important oncoprotein that is overexpressed in various malignant tumors, including HCC, ovarian cancer, gastric cancer, colorectal carcinoma, bladder cancer, breast cancer, nasopharyngeal carcinoma, glioma, NSCLC, myeloma, pancreatic cancer, esophageal carcinoma and cholangiocarcinoma." (PMID 33663617, 2021). "Also, mRNA expression of CHD1L was tested in breast cancer cell lines by quantitative real-time polymerase chain reaction (QRT-PCR) to identify the relationship between expression level and breast cancer subtypes." (PMID 25153161, 2014). "However, the mechanism of CHD1L-related breast cancer development has not yet been revealed." (PMID 25153161, 2014). "However, to date, the expression of CHD1L in breast cancer has not been investigated, thus the clinico-pathological and prognostic value of which remains unknown." (PMID 25153161, 2014). "Analysis results from the second server showed that the expression of CHD1L influenced negatively OS and distant metastasis-free survival (DMFS) (p < 0.05) but not relapse-free survival (RFS) in breast cancer patients." (PMID 37033447, 2023).
colorectal cancer (11 papers, 2013 to 2025). A primary or metastatic malignant neoplasm that affects the colon or rectum. "In breast and colorectal cancer models, pharmacological inhibition of CHD1L results in the entrapment of CHD1L on chromatin, deprotection of nuclear PAR chains, and robust induction of PARthanatos, as measured by AIF translocation to the nucleus." (PMID 40442742, 2025). "These inhibitors demonstrated the ability to suppress CHD1L-mediated TCF/LEF transcriptional activity, reverse EMT, and reduce cancer stem cell (CSC) stemness in colorectal cancer models, mirroring the effects observed with CHD1L knockdown." (PMID 40442742, 2025). "The oncogenic role of CHD1L in tumorigenesis in vitro and in vivo was also observed in colorectal carcinoma." (PMID 24359616, 2013). "Furthermore, overexpression of CHD1L in patients with colorectal carcinoma has been shown to correlate with a large tumor size, deep tumor invasion, a high histological grade and poor disease-free survival." (PMID 25371726, 2014). "The clinical significance of amplification and overexpression of CHD1L have been evaluated in solid tumors, including HCC, ovarian carcinoma, colorectal carcinoma, and bladder cancer." (PMID 24359616, 2013). "Previously, we discovered and optimized the first small-molecule CHD1L inhibitors (CHD1Li), which are allosteric inhibitors of the ATPase activity of CHD1L, inducing the reversion of EMT and cell death in colorectal cancer and display antitumor activity in vivo." (PMID 39201277, 2024).
ovarian carcinoma (10 papers, 2012 to 2023). A malignant neoplasm originating from the surface ovarian epithelium. "This study aimed to investigate candidate circular RNAs (circRNAs) involved in the pathogenic process of ovarian cancer after inhibition of chromodomain helicase DNA binding protein 1-like (CHD1L) and the corresponding mechanism." (PMID 34034740, 2021). "Previously we reported that CHD1L overexpression is significantly associated with the metastasis proceeding of epithelial ovarian cancer (EOC), and may predict a poor prognosis in EOC patients." (PMID 32922205, 2020). "Therefore, CHD1L is not only a biomarker associated with ovarian cancer, but it also appears to be a prognostic factor associated with adverse outcome." (PMID 23020525, 2012). "Regarding ovarian cancer, CHD1L was predicted to correlate with poor OS (p < 0.01), progress-free survival (PFS) (p < 0.01), and post-progression survival (PPS) (p < 0.05)." (PMID 37033447, 2023). "CHD1L protein is overexpressed in human ovarian carcinomas and serves a prognostic biomarker for patients’ survival." (PMID 37046698, 2023). "In this study, we found that CHD1L can promote the migration and invasion of ovarian cancer cells through EMT." (PMID 34034740, 2021). "In our previous study, we have found that the expression of CHD1L was significantly higher in metastatic lesions of ovarian cancer compared to the primary lesions (P < 0.05)." (PMID 34034740, 2021). "In conclusion, CHD1L was significantly upregulated in ovarian cancer tissues and impacted the survival of ovarian cancer patients, suggesting its oncogenic role." (PMID 34034740, 2021). "CHD1L was significantly upregulated in ovarian cancer tissues and patients with higher expression of CHD1L had a shorter relapse-free survival (P < 0.001) and overall survival (P < 0.001)." (PMID 34034740, 2021). "In the present study, to evaluate changes in CHD1L expression in ovarian cancer tissues and normal ovarian tissues, we analyzed the transcriptional levels of CHD1L through several independent bioinformatics databases." (PMID 34034740, 2021). "The prognosis in patients with high CHD1L expression was inferior to those with low CHD1L expression, suggesting that CHD1L was involved in the development and metastasis of ovarian cancer." (PMID 34034740, 2021). "In our previous study, we found that CHD1L expression in metastatic lesions of ovarian cancer was significantly higher than that in primary lesions of ovarian cancer." (PMID 34034740, 2021). "Our previous study demonstrated the presence of CHD1L overexpression in EOC and reported that overexpression of CHD1L protein is significantly correlated with the metastasis proceeding of ovarian carcinoma." (PMID 32922205, 2020). "In the present study, we evaluated CHD1L protein expression levels in six different human ovarian carcinoma cell lines (i.e. ES2, OVCAR-3, A2780, HO-8910 and SKOV3) using western blotting analysis." (PMID 32922205, 2020). "In contrast, knockdown of CHD1L using shRNA inhibited cell invasion in vitro in ovarian carcinoma A2780 and ES2 cell lines." (PMID 32922205, 2020). "It was previously reported that presence of CHD1L over-expression was significantly associated with poorer DFS and OS in both HCC and ovarian carcinoma." (PMID 25153161, 2014). "There is an augmented tendency of CHD1L expression in ovarian carcinoma metastasis than in primary lesions (P<0.05)." (PMID 23020525, 2012). "The clinical/prognostic significance of CHD1L expression in our ovarian carcinoma cohort was assessed." (PMID 23020525, 2012). "In this study, therefore, we examined the expression status of CHD1L protein by IHC in a cohort of ovarian carcinoma tissues (including 102 primary lesions and 44 corresponding metastatic lesions)." (PMID 23020525, 2012). "In this study, immunohistochemistry (IHC) for CHD1L was performed on a tissue microarray (TMA) containing 102 primary ovarian carcinomas and 44 metastatic lesions (omental metastasis)." (PMID 23020525, 2012).
ovarian carcinoma (continued). "Clearly, further studies are needed to elucidate the mechanisms by which CHD1L promoting the development and metastasis of ovarian carcinomas in detail." (PMID 23020525, 2012). "In the present study, IHC staining for CHD1L was performed in a large cohort of ovarian carcinoma patients with complete clinicopathological and follow-up data." (PMID 23020525, 2012). "By univariate survival analysis of the ovarian carcinoma cohorts, positive expression of CHD1L was significantly correlated with shortened patient survival (mean 66.7 months versus 97.4 months, P<0.05)." (PMID 23020525, 2012). "We do not yet know whether there is a direct functional link between SPOCK1 and CHD1L expression in ovarian cancer, and thus more research is required to elucidate the issue." (PMID 37046698, 2023). "Using high-throughput sequencing, we found a circRNA circ-PTK2 that was positively correlated with CHD1L expression, which might be a novel biomarker and therapeutic target for ovarian cancer." (PMID 34034740, 2021). "Furthermore, in our study, we discovered that positive expression of CHD1L was an independent predictor of shorter overall survival in ovarian carcinomas as evidenced by Kaplan-Meier curves and multivariable Cox proportional hazards regression analysis." (PMID 23020525, 2012). "However, the status of CHD1L protein expression in ovarian cancer and its clinical/prognostic significance are obscure." (PMID 23020525, 2012). "For CHD1L protein IHC staining in ovarian carcinoma tissues, positive staining was seen primarily in the nuclei within tumor cells, though occasionally yellowish brown granules could be also observed in the cytoplasm." (PMID 23020525, 2012). "Data have shown that positive expression of the CHD1L protein is significantly associated with the metastasis of ovarian carcinoma; therefore, CHD1L protein expression, as examined by immunohistochemistry, may act as a novel prognostic biomarker for patients with ovarian carcinoma." (PMID 25371726, 2014). "However, the potential oncogenic role and underling mechanisms of CHD1L in ovarian carcinoma have not been investigated." (PMID 23020525, 2012). "In this study, we attempted to suppress chromodomain helicase DNA binding protein 1-like (CHD1L) expression, which is reported to be highly expressed in ovarian carcinoma and correlated to metastasis, and screen potential circRNAs by sequencing." (PMID 34034740, 2021). "Upon further analysis, we found that overexpression of CHD1L was significantly, positively correlated with histological type and advanced pT/pN/pM status, FIGO stage of ovarian carcinomas (P<0.05), and poor survival rates in EOC patients (P<0.001)." (PMID 32922205, 2020). "In ovarian carcinoma HO8910 cell lines, ectopic overexpression of CHD1L substantially induced the invasive and metastasis ability of the cancer cells in vitro." (PMID 32922205, 2020). "In these two studies, similar positive rates of CHD1L over-expression were reported (50.5% for HCC and 51% for ovarian carcinoma)." (PMID 25153161, 2014). "We detected higher CHD1L levels in ovarian cancer samples that had not received treatment, but its expression vanished in samples from patients receiving chemotherapy." (PMID 37046698, 2023). "CHD1L expression is correlated with tumor size and stage in bladder cancer, nasopharyngeal carcinoma and pancreatic cancer in contrast to HCC and ovarian cancer." (PMID 33663617, 2021). "To date, despite these facts, the status of CHD1L protein in ovarian carcinoma tissue and its prognostic significance has not been elucidated." (PMID 23020525, 2012). "Likewise, CHD1L expression was found associated with tumor histopathology and grade, but not tumor stage in HCC and ovarian carcinoma." (PMID 25153161, 2014).
ovarian carcinoma (continued). "In summary, we did find that CHD1L expression, as detected by IHC, was a reliable biomarker for the prognosis of ovarian carcinoma patients, these data supports that CHD1L might act as a prognostic biomarker for patients with ovarian carcinoma independent of clinicopathologic prognostic parameters." (PMID 23020525, 2012). "However, to date, the expression dynamics of CHD1L in ovarian carcinomas has not been investigated, and its clinico-pathological and/or prognostic value in ovarian carcinomas remains unknown." (PMID 23020525, 2012). "Meanwhile, CHD1L expression was not related to tumor stage in our study, which is in line with previous findings in HCC and ovarian carcinoma." (PMID 25153161, 2014).
bladder cancer (6 papers, 2013 to 2023). "As a general finding, CHD1L was attributed to poor prognosis and metastasis in other tumors such as gastric, colorectal, and bladder cancer." (PMID 37033447, 2023). "It was recently demonstrated that, in bladder cancer, CHD1L overexpression was significantly correlated with the histological grade and stage of the tumor." (PMID 25371726, 2014). "Multivariate analysis further demonstrated that CHD1L was an independent prognostic factor for patients with bladder cancer." (PMID 25371726, 2014). "For example, we found that CHD1L protein expression was significantly higher in bladder cancer than in adjacent noncancerous tissues." (PMID 24359616, 2013).
gastric cancer (5 papers, 2015 to 2023). A primary or metastatic malignant neoplasm involving the stomach. "In gastric cancer, up-regulated expression of CHD1L was reported to be correlated with tumor depth, nodal involvement and distant metastasis." (PMID 26360781, 2015). "Gastric cancer represented the most affected cancer type in terms of patients’ survival as the OS, first progression (FP), and PPS were affected with CHD1L expression (p < 0.001)." (PMID 37033447, 2023).
lung carcinoma (5 papers, 2019 to 2025). "Rs17160062 was an Asian ancestry-specific causal variant of lung cancer (MAFAsain=0.09, MAFEuropean=0.008), which located in the fifth intron of CHD1L (chromodomain helicase/ATPase DNA binding protein 1-like gene)." (PMID 31956354, 2020). "For instance, the rs9309336 locus may affect the binding site of the transcription factor FOXP1 and regulate the expression of the CHD1L gene, thereby influencing the risk of lung cancer." (PMID 41049290, 2025). "We thus verified the correlation between ABCB1 expression and NF-κB signaling activation in CHD1L overexpressed lung cancer cell lines." (PMID 30718500, 2019). "Here we demonstrate for the first time that CHD1L can contribute to cisplatin resistance by upregulating the ATP-Binding Cassette Sub-Family B Member (ABCB1) gene in lung cancer cells." (PMID 30718500, 2019). "CHD1L thus activates the ABCB1-NF-κB axis to augment cisplatin resistance of lung cancer." (PMID 37691108, 2023). "CHD1L expression was examined in six different lung cancer cell lines by immunoblotting." (PMID 30718500, 2019).
liver cancer (3 papers, 2021 to 2025). An epithelial or non-epithelial malignant neoplasm that arises from the liver. "In summary, we found that VRK1 interacted with and phosphorylated the CHD1L at S122 site to regulate SNAI1 expression, thus promoting the proliferation, migration and tumor growth of liver cancer cells." (PMID 40234378, 2025). "VRK1 phosphorylates CHD1L at serine 122 to induce the expression of SNAI1, thereby promoting the proliferation, migration and tumor growth of liver cancer cells." (PMID 40234378, 2025). "Finally, liver cancer demonstrated poor OS, disease-specific survival (DSS) (p < 0.01), PFS, and RFS (p < 0.05) with CHD1L expression." (PMID 37033447, 2023).
lymph node metastasis (3 papers, 2015 to 2020). "Similar results have also been observed in human non-small-cell lung cancer, in which overexpression of CHD1L was reported to be associated with lymph node metastasis and/or distant organ metastasis." (PMID 32922205, 2020). "Overexpression of CHD1L in EC was significantly associated with clinical stage (P=0.003) and lymph node metastasis (P<0.01)." (PMID 29088777, 2017). "We found that high CHD1L expression was substantially correlated with lymph node metastasis and clinical stage." (PMID 29088777, 2017). "Overexpression of the CHD1L protein, as well as other clinicopathological variables (clinical stage, differentiation, and lymph node metastasis) that showed significance by univariate analysis, were included in the multivariate analysis." (PMID 29088777, 2017). "In addition, positive CHD1L expression was strongly related to advanced clinical stage (P<0.01), and lymph node metastasis (P<0.01) of EC." (PMID 29088777, 2017).
pancreatic cancer (3 papers, 2020 to 2023). "Analysis of surgical samples from 112 pancreatic cancer patients revealed that the elevation in CHD1L was positively correlated with the patients’ poor survival where the Wnt/β-catenin pathway was linked to the effect of CHD1L on tumor cells proliferation." (PMID 37033447, 2023). "CHD1L influenced cell proliferation by activating the Wnt/β-catenin/TCF pathway in pancreatic cancer." (PMID 33663617, 2021). "Furthermore, CHD1L was involved in pancreatic cancer proliferation through the activation of the Wnt/β-catenin pathway." (PMID 37033447, 2023). "CHD1L overexpression significantly increased β-catenin expression in pancreatic cancer." (PMID 33663617, 2021).
schizophrenia (3 papers, 2014 to 2025). A major psychotic disorder characterized by abnormalities in the perception or expression of reality. "We found that CHD1L is a candidate for autism spectrum disorder (ASD) and attention deficit hyperactivity disorder (ADHD), whereas PRKAB2 and BCL9 have been associated to schizophrenia." (PMID 29922639, 2018).
cholangiocarcinoma (2 papers, 2018 to 2021). A carcinoma that arises from the intrahepatic biliary tree (intrahepatic cholangiocarcinoma) or from the junction, or adjacent to the junction, of the right and left hepatic ducts (hilar cholangiocarcinoma). "CHD1L can inhibit hMLH1 expression in cholangiocarcinoma cells, which was related to the malignant progression and prognosis of cholangiocarcinoma." (PMID 33663617, 2021).